LGR5 (leucine rich repeat containing G protein-coupled receptor 5)
Diseases named in the same sentence as LGR5 in open-access papers (continued):
Sharing a sentence is not in itself a finding about the gene and the disease.
ovarian carcinoma (34 papers, 2011 to 2025). A malignant neoplasm originating from the surface ovarian epithelium. "High LGR5 expression in ovarian cancer was found to be associated with high vasohibin-1 (angiogenesis inhibiting protein-1, infiltration & metastasis marker) expression, a protein associated with early infiltration and metastasis in many cancers." (PMID 39821694, 2025). "Two recent ovarian cancer studies also reported that high LGR5 mRNA expression was significantly associated with increased progression-free survival (PFS) in high grade serous ovarian carcinoma." (PMID 39821694, 2025). "In summary, many studies have found that high LGR5 expression is associated with chemoresistance in breast, cervical, colorectal, hepatic, gastric and ovarian cancer to a wide range of chemotherapy drugs including carboplatin, cisplatin, paclitaxel oxaliplatin, 5-FU and doxorubicin." (PMID 39821694, 2025). "High expression of LGR5 in ovarian cancer cells was associated with resistance to carboplatin." (PMID 39821694, 2025). "However, LGR5 overexpression was associated with reduced migration in ovarian cancer cells (OVCAR-3 and SNU-8)." (PMID 39821694, 2025). "Leucine‐rich repeat‐containing G protein‐coupled receptor 5 (LGR5) plays a vital role in the development of malignant tumors; however, its biological role and underlying mechanism in epithelial ovarian cancer (EOC) remain unclear." (PMID 29777575, 2018). "PE04 ovarian cancer cells programmed into pluripotent stem cells (iPSCs) expressed high levels of LGR5 and were more resistant to cisplatin and taxol compared to parental PEO4 cells." (PMID 39821694, 2025). "This study focused on RSPO1 receptor-binding domain (Fu1-Fu2) that deliver cytotoxic agents or immune-modulating therapies directly to LGR5-expressing ovarian cancer cells and was very effective in a LGR5-rich ovarian cancer xenograft model." (PMID 39821694, 2025). "We recently demonstrated that LGR5-CAR-T cells exhibited anti-tumor activities against ovarian cancer cell lines, primary HGSOC cells, and CRC cell lines in vitro and in vivo." (PMID 39821694, 2025). "Overall, LGR5 levels are low with five of the ovarian cancer and four of the omentum metastasis cases displaying elevated levels of protein in greater than 20% of tumour cells (corresponding to expression score of 1 or greater)." (PMID 39169164, 2024). "Overall, our analyses of pan-cancer LGR5 transcript levels is consistent with a previous study ranking colon and rectum, endometrial carcinoma and ovarian cancers as amongst the highest LGR5 expressors relative to other cancers and to their tissues of origin." (PMID 39169164, 2024). "Pre-clinical anti-tumour activity of LGR5-specific CAR T-cells has recently been demonstrated in models of ovarian cancer, while LGR5-specific CAR NK cells have also been described." (PMID 36831514, 2023). "Next, we investigated LGR5 expression in other histologic types of ovarian carcinomas, including 44 mucinous carcinomas (MCs), 47 endometrioid carcinomas (ECs), and 48 clear cell carcinomas (CCCs)." (PMID 35778589, 2022). "In the OSE lineage, a subpopulation of LGR5+ cells have been identified as the OSE stem cells to sustain this lineage and have also been implicated as the cellular origin of ovarian cancer (particularly those in the ovarian hilum region)." (PMID 35159108, 2022). "Studies on liver cancer, colorectal tumors, basal cell carcinoma, ovarian cancer, and other tumors have shown that LGR5 promotes cell proliferation and invasion in tumor cells, and leads to tumor stem cell-like characteristics, resulting in a poor prognosis." (PMID 36288272, 2022). "In contrast, significant levels of stromal LGR5 expression were observed in all histological types of ovarian carcinomas." (PMID 35778589, 2022).
ovarian carcinoma (continued). "Although gene mutations in the Wnt/β-catenin pathway are relatively uncommon in ovarian cancer in general, in this study, we observed high levels of LGR5 expression in all subtypes of ovarian carcinomas, except MCs." (PMID 35778589, 2022). "In this study, we thoroughly investigated LGR5 expression in human ovaries and fallopian tubes as well as related benign and malignant ovarian tumors." (PMID 35778589, 2022). "The present study was designed to determine the pattern of the expressions of miR-340, LGR5, and FOXO1 genes in ovarian cancer tissue samples as well as their association with drug resistance in ovarian cancer cell lines." (PMID 33718760, 2021). "Support for this hierarchy also comes from ovarian cancer cell-of-origin studies in mice, where a lineage-tracing study suggested LGR5+, ALDH+/CD133+ ovarian surface-repopulating stem cells were found in the oviductal hila of mice." (PMID 32194856, 2020). "Next, we assessed LGR5 expression levels by qPCR and Western blotting in three ovarian cancer cell lines (SKOV3, Hey, HO8910)." (PMID 29777575, 2018). "In the present study, we provide evidence that LGR5 can promote ovarian cancer progression via Notch1 signaling in EOC." (PMID 29777575, 2018). "For the first time, our study examined the effects of LGR5 on the biological behavior of epithelial ovarian cancer and explored the relationship between LGR5 and Notch1 pathway in epithelial ovarian cancer." (PMID 29777575, 2018). "In this study, we investigated the expression of LGR5 at the mRNA and protein levels in human ovarian cancer and verified correlations between LGR5 expression and clinicopathological parameters." (PMID 29777575, 2018). "LGR5 should be further considered as a marker of ovarian endometriosis lesions, and its role in the development of ovarian cancer should be further studied." (PMID 30577586, 2018). "In accordance with our results, McClanahan and colleagues observed that in both colorectal and ovarian carcinomas expression of LGR5/GPR49 mRNA was high in stage I and II tumors and appears to decrease in stage III and IV tumors." (PMID 21978106, 2011). "As a stem cell marker, LGR5 regulates Wnt/β-catenin signaling and contributes to tumor initiation, progression, and therapy resistance in cancers such as colorectal, gastric, liver, and ovarian cancer." (PMID 41194856, 2025). "LGR5-KD in ovarian cancer (HO8910) cells significantly inhibited cell proliferation." (PMID 39821694, 2025). "Further research suggested that LGR5 + stem/progenitor cells are responsible for ovarian epithelium regeneration and may be involved in ovarian cancer initiation." (PMID 39821694, 2025). "To date, only two studies investigated the role of LGR5 in ovarian cancer migration or invasion." (PMID 39821694, 2025). "LGR5 is involved in promoting tumor progression via EMT and WNT/β-catenin pathways and increased LGR5 expression is associated with chemotherapy resistance and recurrence in different cancers including breast, cervical, CRC, gastric, HCC and ovarian carcinoma." (PMID 39821694, 2025). "LGR5 plays a role in tumor progression by promoting cancer cell migration, invasion, metastasis, and angiogenesis in many cancers including colorectal, brain, gastric, and ovarian cancer." (PMID 39821694, 2025). "Our transcription data ranked ovarian cancer as one of the highest LGR5-expressing cancers." (PMID 39169164, 2024). "In ovarian cancer, LGR5 expression is a favorable prognostic factor." (PMID 38787285, 2024). "Interestingly, we have found that ovarian cancer tissues with high expressions of PD-L1 were associated with high expressions of stem cells expressing CD44 and LGR5." (PMID 36604635, 2023). "The proportion of epithelial and/or stromal positivity (cutoff value: 40 of H-score) varied between subtypes, and we suggest three categories of ovarian carcinomas based on LGR5 expression; stromal-predominant type (LGSC), epithelial-stromal type (HGSC, CCC, EC), and low type (MC)." (PMID 35778589, 2022).
ovarian carcinoma (continued). "In addition, further studies with a larger size of samples are also required to confirm the prognostic significance of LGR5 not only in HGSC but also in other types of ovary carcinomas." (PMID 35778589, 2022). "Similar to the findings in ovarian cancer, in rare incidences, LGR5-/KRT20+ cells could revert into LGR5+/KRT20+, form colonies and proliferate." (PMID 32194856, 2020). "Moreover, Oncomine LGR5 gene expression data from patients obtained in RNA‐Seq experiments showed that the expression levels of LGR5 in ovarian cancer patients were augmented in stages III and IV, relative to that in normal tissues." (PMID 29777575, 2018). "Taken together, our findings indicate that LGR5 expression may have a critical role in epithelial ovarian cancer tumorigenesis." (PMID 29777575, 2018). "It has been reported that LGR5 is overexpressed in ovarian cancer 9; however, its role in cell proliferation, migration, and invasion, and the underlying molecular mechanisms remain unclear." (PMID 29777575, 2018). "However, the role of LGR5 in ectopic lesions and its relation to the promotion of endometriosis and/or ovarian cancer is less understood." (PMID 30577586, 2018). "Other works have supported this idea since LGR5+ seems to be related to progression of different cancers, such as colon, papillary thyroid, breast, and ovarian cancers by promoting epithelial ovarian cancer proliferation, metastasis, and epithelial–mesenchymal transition (EMT)." (PMID 30577586, 2018). "A colony formation assay demonstrated that LGR5 could increase the number of foci formed by ovarian cancer cells and promote tumor growth." (PMID 29777575, 2018). "LGR5 (leucine rich-repeat G protein-coupled receptor 5) has been shown to maintain adult intestinal stem cells, postembryonic development, and is expressed in ovarian cancer." (PMID 29190952, 2017). "However, owing to lack of data for fallopian tubes in the TCGA database, the presumptive tissue of origin for ovarian cancer, we were unable to determine whether this represents malignancy-specific increases in LGR5 overexpression." (PMID 39169164, 2024). "Thus, we examined whether Wnt signaling activity is responsible for the high levels of LGR5 expression observed in ovarian carcinomas by examining the correlation between nuclear β-catenin and LGR5 expression." (PMID 35778589, 2022). "Furthermore, LGR5 is overexpressed in ovarian cancer tissue compared to normal tissue." (PMID 30577586, 2018). "Leucine-rich repeat-containing G protein–coupled receptor 5 (LGR5) is a bona fide marker of adult stem cells in several epithelial tissues, most notably in the intestinal crypts, and is highly up-regulated in many colorectal, hepatocellular, and ovarian cancers." (PMID 28739799, 2017). "Lower levels of cyclin D1 and C-Myc were also observed in LGR5-KD SKOV3 cells compared to parental cells, suggesting that LGR5 can promote cell proliferation, cell growth and cancer metastasis in epithelial ovarian cancer." (PMID 39821694, 2025). "The detection of stem cells that express LGR5 and ALDH have been reported in ovarian cancer, and the expressions of the stem cell markers correlates positively with cancer stage." (PMID 41154374, 2025). "The stem cell markers LGR5, Oct4, and CD44 were highly expressed in the ovarian cancer cell lines ES2, OVCAR8, and OVCAR3." (PMID 38275417, 2024). "We probed 24 fallopian tube biopsies with α-LGR5 and α–β-catenin alongside a TMA containing 28 ovarian cancer and 14 omentum metastasis cases." (PMID 39169164, 2024). "generated LGR5-redirected CAR-Ts and set out to evaluate their tumoricidal effects on different cell lines of ovarian cancer origin and patient-derived tumor cells in monolayer and 3D culture conditions." (PMID 38146364, 2023). "For further demonstration of the ovarian cancer microenvironment, we have investigated cancer stem cells expressing CD44, LGR5 and ALDH2." (PMID 36604635, 2023).
ovarian carcinoma (continued). "Wang and colleagues have reported the expression of LGR5 in a variety of ovarian cancer cell lines (including OAW28, COV318, and COV362), and have also reported its elevated expression level in ovarian cancer tissue samples in patients who had relapsed tumors." (PMID 38146364, 2023). "Compare to the paired adjacent normal tissues, a significant increase in the expression of the LGR5 gene and a significant decrease in expression of the miR-340 and FOXO1 genes were observed in the tissue samples of the patients with ovarian cancer." (PMID 33718760, 2021). "Various specific markers including ALDH1/2, CD133, CD117, CD24, CD34, CD44, CD133, EpCAM, LGR5 and LY6A have been employed for isolation and characterization of ovarian CSCs from ovarian cancer cell lines, patients’ tumors and ascites." (PMID 30121075, 2018). "We evaluated LGR5 expression in EOC cell lines and tissues from ovarian cancer patients by qPCR, Western blotting, and immunohistochemical analysis." (PMID 29777575, 2018). "To validate that VJ targets other CSC populations in addition to ALDH1+ CSC population, we examined the effect of VJ on expression of genes for NANOG, LGR5 and OCT4, reported to be present in ovarian cancer." (PMID 29190952, 2017). "LGR5 silencing also reduced tumorigenesis in vivo using CRC and ovarian cancer models." (PMID 39821694, 2025). "While there was a slight overall increase in LGR5 protein levels in ovarian cancer relative to fallopian tube epithelia we did not observe the corresponding increase for the omentum metastasis cases." (PMID 39169164, 2024). "Similarly, LGR5 and LGR6 are two members of the leucine rich repeat (LGR) containing GPCRs family and are expressed on the surface of ovarian cancer tissues." (PMID 40836974, 2024). "LGR5 has attracted a great deal of therapeutic interest owing to its overexpression in human malignancies such as CRC, HCC, gastric and ovarian cancers, basal cell carcinoma, ER-negative breast cancers, glioblastoma, and certain B-cell malignancies." (PMID 39169164, 2024). "The increased expression of LGR5 markedly promotes the growth and the EMT of ovarian cancer cells." (PMID 37628927, 2023). "Several receptors have been found to be upregulated in ovarian cancer tissues, including growth hormone releasing hormone receptor (GHRHR), GRPR, leucine-rich repeat-containing G-protein coupled receptor 5 (LGR5), oxytocin receptor (OXTR) and parathyroid hormone 2 receptor (PTH2R)." (PMID 35625966, 2022). "The LGR5, FOXO1, and miR-340 genes can be targeted for early diagnosis and more accurate treatment of ovarian cancer and may prevent some of the ovarian cancer complications such as infertility." (PMID 33718760, 2021). "Ovarian cancer stem cells are widely researched using established markers such as aldehyde dehydrogenase (ALDH1) or leucine-rich, repeat-containing G protein-coupled receptor 5 (LGR5), mostly in ovarian cancer cell lines (e.g., OVCAR3, SKOV3, IGROV1) in vitro." (PMID 26940129, 2016). "However, the role of miR-340 and its potential association with the LGR5 and FOXO1 genes as well as their effects on the drug resistance in ovarian cancer have not been addressed till now." (PMID 33718760, 2021).
intestinal cancer (32 papers, 2011 to 2025). "Using the established Lgr5‐deficient mouse model, they also demonstrated that Lgr5+ crypt stem cells are the cells of origin of intestinal cancer." (PMID 41346572, 2025). "Loss of CDH17 resulted in a marked down-regulation of the intestinal cancer stem cell (CSC) marker LGR5, leading to the inhibition of Wnt/β-catenin signaling, suppression of pluripotency genes such as MYC, and a subsequent reduction in stemness properties." (PMID 40595509, 2025). "Recently, expression of leucine-rich repeat-containing G-protein coupled receptor 5 (LGR5) has been clearly associated with the initiation of primary intestinal cancers as well as CRC-derived liver metastases." (PMID 33255928, 2020). "In the intestine, mutations in long-lived stem cells (Lgr5+), expressing leucine-rich repeat-containing G-protein coupled receptor 5), located at the crypt bottoms, are believed to result in intestinal cancer." (PMID 28230774, 2017). "Marker gene analysis corroborated these findings, revealing that S1 cells highly expressed LGR5, a well‐established marker of intestinal cancer stem‐like cells." (PMID 40661135, 2025). "Lgr5+ epithelial stem cells provide a source of cancers in the epithelium, colon, and stomach, and tumor-resident Lgr5+ cells in intestinal cancers can be functional stem cells responsible for the progression of cancer and related diseases." (PMID 35743714, 2022). "LGR5 + stem cells are involved in the process of oncogenesis, acting as tumor-initiating cells of intestinal cancer and fueling tumor growth." (PMID 36372898, 2022). "Using Cre-Loxp to delete Apc in mice Lgr5+ ISCs leads to rapid formation of intestinal adenomas, strongly indicating that Lgr5+ ISCs are the cells of origin for intestinal cancer." (PMID 35885015, 2022). "Intriguingly, OPCs suppressed spheroid derived cancer stem-like cell formation and decreased the expression of intestinal cancer stem cell markers including LGR5, CD44 and CD133." (PMID 29463813, 2018). "It will further highlight recent studies indicating the plasticity or redundancy of LGR5+ cells in intestinal cancer progression and assess the overall merit of therapeutically targeting LGR5 in CRC." (PMID 29844449, 2018). "Previous reports of Lgr5-positive cells localized to the upper crypts have only been descried for intestinal cancer." (PMID 27979825, 2017). "Like the normal epithelium, intestinal cancers also contain Lgr5 expressing stem cells and these cells share properties of the normal Lgr5 stem cells." (PMID 29127379, 2017). "In line with human intestinal cancers, Lgr5 and Ascl2 were overexpressed in all three tumor models indicating an increased number of stem-like cells as a result of aberrant Wnt signaling." (PMID 27811361, 2016). "As Lgr5+ stem cells are the cell of origin for intestinal cancer and also a marker of intestinal cancer stem cells, this data opens new avenues of research to determine the therapeutic benefit of inhibiting Fzd7 to specifically target these cells." (PMID 27196929, 2016). "Intestinal stem cells expressing leucine-rich repeat-containing G-protein coupled receptor 5 (Lgr5) are cycling stem cells required for maintaining tissues in steady state, and they act as cells-of-origin in intestinal cancer." (PMID 25832104, 2015). "It should be stressed that the results obtained in mice indicating Lgr5+ and/or Bmi1+ crypt stem cells as the cells-of-origin of bowel cancer most likely pertain to the familiar or sporadic CRC." (PMID 24920319, 2014). "For example, Morgan RG thought there is the plasticity or redundancy of LGR5 + cells in intestinal cancer progression and targeting LGR5 may be a great therapeutical strategy for CRC." (PMID 33713277, 2021). "This may indicate that the tumor promoting function of Pygo2 in the Ctnnb1 GOF model may be partly regulated by the induction of Lgr5-positive stem-like cells that are known to be the origin of intestinal cancer." (PMID 27811361, 2016).